BCL2 (BCL2 apoptosis regulator)
Diseases named in the same sentence as BCL2 in open-access papers (continued):
Sharing a sentence is not in itself a finding about the gene and the disease.
Insulin resistance (18 papers, 2016 to 2025). Increased resistance towards insulin, that is, diminished effectiveness of insulin in reducing blood glucose levels. "Integration of compound, target, and pathway data positioned IL-6 as a central mediator, interacting with MAPK1, MAPK3, MAPK14, PTGS2, and BCL2, genes associated with inflammation-induced insulin resistance and adipocyte dysfunction." (PMID 41382285, 2025). "Astaxanthin exhibited a protective effect against apoptosis by regulating p38MAPK/bcl-2/caspase-3 pathway, and ameliorated insulin resistance by activating the PTP1B/PI3K/Akt pathway." (PMID 39300527, 2024). "However, the Bax/Bcl-2 ratio decreased significantly in the VNS group suggesting that VNS attenuated cardiac apoptosis in obese-insulin resistance." (PMID 26830020, 2016). "The diabetic control group exhibited pancreatic dysfunction as evidenced by the reduction in serum insulin, homeostasis model assessment of ß-cell function (HOMA-β), expressions of PI3K/AKT, Bcl-2, and PCNA combined with an elevation in homeostatic model assessment of insulin resistance (HOMA-IR)." (PMID 35308202, 2022).
psoriasis (18 papers, 2018 to 2025). An autoimmune condition characterized by red, well-delineated plaques with silvery scales that are usually on the extensor surfaces and scalp. "Prolonged keratinocyte survival and psoriasis persistence are caused by an imbalance between the apoptotic regulators Bcl-2 and Bax." (PMID 40818978, 2025). "None of the previous studies have directly studied the association of Bcl-2 in psoriasiform dermatitis compared with psoriasis." (PMID 39552957, 2024). "There are many studies done in the past, which tried to understand the Bcl-2 expressivity in different compartments of psoriasis epidermis and dermis and the likely underlying pathogenetic mechanisms." (PMID 39552957, 2024). "We also found the association of Bcl-2 positivity among cases of psoriasis and psoriasiform lesions." (PMID 39552957, 2024). "P. clypearia may ameliorate inflammation in psoriasis mice by modulating genes such as Hspa1a, Hspa1b, mt-Nd4l, mt-Nd5, mt-Nd6, Bcl2, Asns, Trib3, and associated pathways related to energy metabolism, cell growth, and apoptosis." (PMID 41385507, 2025). "Interestingly, Th17 cells (a subset of CD4+ T cells), which play a crucial role in pathogenesis of psoriasis, exhibit a lower expression of clusterin and a higher expression of Bcl-2, which make them less susceptible to apoptosis." (PMID 32764517, 2020). "Nitidine chloride relieves psoriasis skin lesions and inflammation by inhibiting HaCaT proliferation, inducing S phase cell cycle arrest, and significantly downregulating Bcl-2." (PMID 41385507, 2025). "This study explores regenerative therapies—exosomes, mesenchymal stem cells (MSCs), epigallocatechin-3-gallate nanoparticles (EGN), and EGN-loaded exosomes (EGN-Exo)—in regulating psoriasis-related markers (IL-6, IL-4, Bcl-2, Bax, NF-κB, CDC25B)." (PMID 40818978, 2025). "Bcl-2 positivity and its distribution among different compartments were compared among cases of psoriasis and psoriasiform dermatitis." (PMID 39552957, 2024). "Psoriasis cases demonstrated more significant Bcl-2 positivity in dermal lymphocytes and basal layers than psoriasiform dermatitis cases." (PMID 39552957, 2024). "Later many studies have demonstrated the significantly increased expression of Bcl-2 in the lymphocytes of psoriasis skin dermal layers." (PMID 39552957, 2024). "Increased Bcl-2 expression in psoriasis cases compared with other psoriasiform dermatitis lesions implies the more chronic and recurrent nature of the disease." (PMID 39552957, 2024). "In our study, we have used a primary antihuman antibody against Bcl-2 (rabbit monoclonal antibody from path-in-situ), and we have analyzed the expressivity of Bcl-2 in different compartments of psoriasis and psoriasiform dermatitis skin lesions." (PMID 39552957, 2024). "We also report that Bcl-2 shows more significant positivity in basal keratinocytes and dermal lymphocytes in psoriasis lesions than in psoriasiform dermatitis cases." (PMID 39552957, 2024). "Bcl-2 expression was seen in dermal lymphocytes in all psoriasis and psoriasiform lesions with significantly stronger positive expression compared to basal and supra-basal layers." (PMID 39552957, 2024). "As there is a histopathological overlap of features in psoriasis and psoriasiform dermatitis cases, we suggest that Bcl-2 can be used as a marker in differentiating these conditions for accurate diagnosis and targeted therapeutic approaches." (PMID 39552957, 2024). "At the same time, up-regulation of caspase-3, cleaved caspase-3, and Bax and down-regulation of Bcl-2 resulting from TBTDC NP-PDT in LPS-induced psoriasis keratinocytes were significantly rescued by NAC, as detected by WB analysis." (PMID 39109246, 2024). "We found that Bcl-2 expression was present in almost all cases of psoriasis and psoriasiform lesions." (PMID 39552957, 2024).
psoriasis (continued). "lncRNA-RP6- 65G23.1 is a significant upregulated lncRNA in psoriasis that promotes keratinocyte proliferation and suppression of apoptosis by modifying the expression of Bcl-xl, Bcl2 and the ERK1/2-AKT signaling pathway." (PMID 37628670, 2023). "NF-κB, acted as a transcription factor of Bcl-2, is a crucial regulatory pathway in cellular proliferation, differentiation, and apoptosis in the pathogenesis of psoriasis." (PMID 37739945, 2023). "The ELISA results for the expression levels of the Bax (pro-apoptotic marker) and Bcl2 (anti-apoptotic marker) showed that in the psoriasis sample, the Bax level increased to 2.9, which is more than the normal range that is 1, but after the treatments were applied, the level of Bax decreased." (PMID 40818978, 2025). "Additionally, studies have shown that other genes such as FAS, BAX, and BCL-2 also exhibit different expression patterns in the skin of psoriasis patients, and these genes are directly involved in the regulation of apoptosis." (PMID 40557155, 2025). "Similarly, the pro-apoptotic marker Bax was found to be upregulated in psoriasis samples, with levels increasing to 2.9 compared to the normal range of 1, while the anti-apoptotic marker Bcl-2 was downregulated to 0.3." (PMID 40818978, 2025). "Second, since psoriasis is a dynamic disease, the level of expression of Bcl-2 may vary in different stages of the disease." (PMID 39552957, 2024). "Psoriasiform dermatitis cases were found to have a similar pattern of distribution of Bcl-2 as in psoriasis cases, but these cases had mainly weak to moderate positivity compared to psoriasis cases which had mainly moderate to strong positivity of Bcl-2 staining." (PMID 39552957, 2024). "In addition, many studies that compared psoriasis skin with normal skin have reported the decreased expression of Bcl-2 in psoriasis keratinocytes." (PMID 39552957, 2024). "Hence, we aim to analyze the immunohistochemical (IHC) expression of Bcl-2 in different skin compartments in psoriasis as well as psoriasiform dermatitis lesions in this study." (PMID 39552957, 2024). "First, we haven’t analyzed Bcl-2 expression in different forms of psoriasis, as it may show differences in different morphological patterns." (PMID 39552957, 2024). "This could probably form the basis of treatment by anti-Bcl-2 antibodies in more chronic and recurrent cases of psoriasis." (PMID 39552957, 2024). "The protein expression of the of the proliferation markers PCNA and the anti-apoptotic protein BCL2 was observed to be markedly increased in the IMQ psoriasis induced group, while their expression levels were significantly declined in all the treatment groups used in the current study." (PMID 37010718, 2023). "Additionally, it was mentioned previously that activation of NF-κB can increase the transcription of anti-apoptotic protein (BCL2), inhibiting apoptosis of skin cells in psoriasis." (PMID 37010718, 2023). "We noted that Bcl-2 was more strongly expressed in basal and dermal lymphocytes of psoriasis cases than in psoriasiform dermatitis cases, which could probably explain the more aggressive, chronic, and recurrent nature of psoriasis compared to other psoriasiform dermatitis lesions." (PMID 39552957, 2024). "In addition, BIRC5, NAMPT and BCL2 may affect the development of psoriasis by regulating autophagy." (PMID 38129460, 2023). "The results indicated that P. clypearia may affect the energy metabolism, cell growth and apoptosis by regulating genes such as Hspa1a, Hspa1b, mt-Nd4l, mt-Nd5, mt-Nd6, Bcl-2, Asns, Trib3, GzmA, CTSG, etc, thereby mitigating psoriasis-related inflammation." (PMID 41385507, 2025).
psoriasis (continued). "Bcl-2 expression was observed in normal basal keratinocytes, whereas it was negative in the epidermis of psoriasis patients, according to one study." (PMID 39552957, 2024). "Further research studied the significant expression of Bcl-2 in lymphocytes in the dermis of psoriasis lesions compared to non-psoriatic lesions." (PMID 39552957, 2024). "The dynamic nature of the disease was explained in literature by decreased expression of Bcl-2 in psoriasis compared to normal skin, which was not studied in this study." (PMID 39552957, 2024). "The mRNA expression levels of the pro-apoptosis gene Bax (P < 0.05) and the anti-apoptosis gene Bcl-xL (P < 0.05) were significantly upregulated in psoriasis lesions (n = 23) compared with HC (n = 12) by RT-qPCR, while Bcl-2 was not changed." (PMID 32632545, 2020). "As per another study, neither normal nor psoriasis epidermis expressed Bcl-2." (PMID 39552957, 2024).
solitary fibrous tumor (18 papers, 2009 to 2025). Solitary fibrous tumor (SFT) represents a diverse group of ubiquitous rare spindle cell neoplasms that may be benign or malignant and that most frequently arises from the pleura and peritoneum and rarely from other sites such as head and neck, liver and skeletal muscle. "Positive expression for CD99 and Bcl2 is present in both sinonasal sarcoma and solitary fibrous tumors." (PMID 41226013, 2025). "Positive staining of the tumor markers, CD34+, CD99+ and Bcl-2+, was confirmed by pathological examination following surgery, and a solitary fibrous tumor of the spermatic cord was diagnosed." (PMID 25452776, 2015). "The stromal cells are bcl-2 positive and it has been postulated that neoplastic growth may occur through the pathway similar to solitary fibrous tumor." (PMID 21532907, 2009). "Among these conditions is the intrapulmonary solitary fibrous tumor, which is usually positive for CD34, BCL2, CD99, and, more recently, STAT6." (PMID 40026987, 2025). "In the present case, focal positivity for STAT6, Bcl-2, and CD99 supported the diagnosis of dedifferentiated solitary fibrous tumor (DSFT)." (PMID 40728762, 2025). "Immunohistochemical analysis demonstrated positivity for CD34, STAT6, MyoD1, α-SMA, Bcl-2, and CD99, confirming the diagnosis of extrapleural dedifferentiated solitary fibrous tumor (DSFT)." (PMID 40728762, 2025). "Other studies show that solitary fibrous tumors express CD34 in 80–95% cases and CD99 in 70%, while infrequently expressing Bcl2, epithelial membrane antigen, and smooth muscle actin (20–35% of cases)." (PMID 41226013, 2025). "This characteristic helps distinguish desmoid tumors from other tumors that show fibroblastic proliferation, such as solitary fibrous tumors or nodular fasciitis, which more commonly demonstrate positivity for CD34, vimentin, Bcl-2 and CD99." (PMID 41226994, 2025). "A biopsy of the mass showed spindle cells positive for BCL-2, CD34, and STAT 6, indicative of a solitary fibrous tumor." (PMID 36041816, 2022). "Hemangiopericytomas can have histological overlap with solitary fibrous tumor, but CD34 and Bcl-2 staining is weak and patchy." (PMID 22805173, 2012). "Bcl-2 and CD99 immunohistochemistry were used to distinguish a hemangiopericytoma from a solitary fibrous tumor because a solitary fibrous tumor is positive for Bcl-2 and CD99." (PMID 20205807, 2010). "IHC staining plays a crucial diagnostic role, in that solitary fibrous tumors are positive for CD34 and bcl-2, but negative for calretinin and HBME-1." (PMID 27599565, 2016). "Furthermore, CD34, S100, Bcl-2, and STAT-6 expression was negative, ruling out the possibility of a solitary fibrous tumor and malignant peripheral nerve sheath tumor (MPNST)." (PMID 32430041, 2020). "But these expressions were not decisive in the differentiation between solitary fibrous tumor and pancreatic hamartoma, because CD34 was positive for both tumors, and CD99 and bcl-2 expressions were not elucidated in the previous cases of pancreatic hamartomas." (PMID 26425382, 2015). "However spindle cells in solitary fibrous tumor also express CD99 and bcl-2, which are negative for dermatofibrosarcoma protuberans." (PMID 23199263, 2012). "However the immunoprofile of the neoplastic cells was typical of a solitary fibrous tumor (negative for EMA, strongly positive for CD34, vimentin and Bcl-2)." (PMID 22805173, 2012).
T cell lymphoma (18 papers, 2008 to 2024). "Strikingly, p27 deficiency synergistically cooperates with Bcl-2 to increase T cell hyperplasia and development of spontaneous T cell lymphomas." (PMID 18382684, 2008). "The forced expression of Bcl-2 protected from GD3-induced apoptosis in T cell lymphoma CEM cells and mouse oligodendrocytes suggested that relevant GD3 targets are under Bcl-2 control, which we observed in the case of GalCer, but with an opposite effect." (PMID 38254878, 2024). "Patients with advanced T cell lymphomas (TCLs) have limited therapeutic options and poor outcomes in part because their TCLs evade apoptosis through upregulation of anti-apoptotic Bcl-2 proteins." (PMID 32677976, 2020). "As T cell lymphoma is a more aggressive disease, the higher Bcl-2/BAX ratio indicates resistance to apoptosis." (PMID 31676831, 2019). "We additionally observed phenotypic bias (selection specific to B cell or T cell lymphoma, the yellow heat map) and genotypic bias (selection in cooperation with the BCL2 transgenes, the green heat map)." (PMID 29985390, 2018). "Here, the authors show that the THZ1, a CDK7 inhibitor, suppresses STAT transcriptional activity leading to apoptosis and sensitization to BCL2 inhibitors in T-cell lymphomas." (PMID 28134252, 2017). "This response was independent of Bcl-2 and Bcl-xL, suggesting possible differences in the contribution of these Bcl-2 family member proteins to malignant cell survival across various T cell lymphomas." (PMID 31684088, 2019). "For example, the BCL2 inhibitor venetoclax is approved for the treatment of several haematological malignancies, and the dual CIAP1/XIAP inhibitor tolinapant was granted orphan drug designation from the United States Food and Drugs Administration (FDA) for the treatment of T-cell lymphoma in 2020." (PMID 39886119, 2024).
Anxiety (17 papers, 2012 to 2026). Intense feelings of nervousness, tension, or panic often arise in response to interpersonal stresses. "Here it is important to note that elevated levels of Bcl-2 are associated with decreased anxiety, while Bcl-2 deficiency increases anxiety." (PMID 29027157, 2017). "On the other hand, mice with a heterozygous knock-out of the Bcl-2 gene exhibit Bcl-2 deficiency and increased anxiety behavior." (PMID 29027157, 2017). "Transgenic mice over-expressing Bcl-2 in the brain showed a decrease in anxiety and neophobia, whereas Bcl-2 knockout mice showed a significant increase in anxiety-like behavior, suggesting the involvement of Bcl-2 in anxiety disorders." (PMID 23152871, 2012). "Similarly, transgenic mice over-expressing anti-apoptotic gene Bcl-2 decreased neuronal cell death, altered anxiety behavior, and impaired learning ability." (PMID 30003515, 2019). "Bcl-2 manipulation might also be related to anxiety as mice with an additional Bcl-2 transgene, and therefore elevated Bcl-2 levels, exhibited less anxiety behavior." (PMID 29027157, 2017). "Furthermore, MLT might be effective against chronic NP-mediated anxiety- and depressive-like behaviors by regulating Bax/Bcl2 and NF-κB/NLRP3 signaling pathways in the PFC and HC." (PMID 36747075, 2023). "In summary, exercise can effectively promote hippocampal neurogenesis and inhibit hippocampal cell apoptosis through the Caspase3/BCL‐2/BAX pathway, and then contributes to the amelioration of anxiety behavior in menopausal mice." (PMID 37402694, 2023). "Therefore, JSO ameliorates anxiety-like behaviors by upregulating BDNF expression, suppressing hyperactivation of the PI3K/AKT/mTOR signaling pathway, and reducing the BAX/BCL-2 ratio, thereby enhancing neuronal survival and synaptic plasticity." (PMID 40509387, 2025). "In a rat model of PTSD, four weeks of treadmill exercise protocol ameliorated stress-induced enhanced anxiety levels, serum CORT, the BDNF protein level in the hippocampus and serum, and apoptosis markers (Bax, Bcl-2, and Caspase 3) as compared to the sedentary rats." (PMID 36362131, 2022).